TNF (tumor necrosis factor)
Diseases named in the same sentence as TNF in open-access papers (continued):
Sharing a sentence is not in itself a finding about the gene and the disease.
tumor (continued). "Using human cancer cell lines, morphine could dose-dependently suppress tumor cell growth via the inhibition of TNF-α release, which may be associated with reduced NF-κB pathway activation." (PMID 36765695, 2023). "However, the underlying anti-tumor and anti-proliferative mechanisms of NF-κB p65 (RelA) and TNFα are still poorly defined." (PMID 37892820, 2023). "Indeed, expression of PD-L1 on tumor cells has been implicated in the inhibition of signaling pathways promoting TNF production." (PMID 38020877, 2023). "However, tumor-associated pDCs have been shown to promote angiogenesis in vivo through the production of the proangiogenic cytokines TNF-α and CXCL8." (PMID 36949244, 2023). "TNF-based immunocytokines also display a very pronounced cytotoxic effect against the endothelial cells, which may be a cause of tumor vessel lesions." (PMID 36839658, 2023). "Surprisingly, TNF-α has been proposed to be used for cancer treatment, as it possesses the ability to induce vascular hyperpermeability and destruction of vascular lining in tumor-associated vasculature." (PMID 36986550, 2023). "Our results showed elevated plasma levels of FGF, IL-6, IL-8, M-CSF, VEGF, TNF-alpha, and IL-17a, molecules previously associated with larger tumor size, metastasis, and poor prognosis, as well as persistent HPV infection in older women with evidence of an immune deficit." (PMID 38114557, 2023). "In addition, when performing GSEA for the Hallmark for “TNFα signaling via NFκB” we confirmed its enrichment in KPC-HAPLN1 tumor cells." (PMID 37095087, 2023). "The repolarization of macrophages from M2 to M1 phenotype in tumor tissue may be caused by M1-stimulated macrophages entering the tumor, actively producing TNF-α, ROS, and high iNOS/NO levels." (PMID 38001420, 2023). "TNF-α is an exceptionally pleiotropic cytokine that has a crucial job in protection, insusceptible homeostasis, and irritations and plays an important role as an inflammation mediator associated with carcinogenesis and tumor progression." (PMID 37048097, 2023). "In addition, TNFα is a key tumor-promoting effector molecule secreted by tumor-associated macrophages." (PMID 37787041, 2023). "Moreover, it has been proposed that TNF is implicated in tumor angiogenesis and cell death, thereby facilitating tumor advancement and metastasis." (PMID 38239355, 2023). "Another upregulated (1.78-FC) gene of interest was PPP1R1C, and increased expression may increase tumor cell susceptibility to TNF-induced apoptosis." (PMID 37446056, 2023). "TNF-α leads to increased vascular permeability of tumor vessels resulting in increased concentrations of cytotoxic drugs within the tumor and selective destruction of tumor associated vessels by apoptosis and inflammation." (PMID 36672397, 2023). "Activation of SRC in tumor-associated macrophages is induced by tumor-derived cytokines and chemokines (e.g., TNF, MIP, SDF-1), which amplify the production of inflammatory cytokines (e.g., TNF, IL1β, IL6) to reciprocally activate SRC in a feed-forward loop and promote PDAC progression." (PMID 37120696, 2023). "The combination of both nanoformulations transformed the ‘cold’ TME into a ‘hot’ one, supported by increased numbers of CD8+ T cells, CD4+ T cells, dendritic cells, IFN-γ, TNF-α, and IL-12 and reduced numbers of MDSCs, Tregs, tumor-associated macrophages (M2), IL-4, IL-6, and IL-10." (PMID 37600822, 2023). "Metformin was reported to demonstrate an ability to reject various solid tumors in normal, but not T-cell-deficient SCID mice and it increased the numbers of CD8+ tumor-infiltrating lymphocytes (TILs), with multiple cytokine production, i.e., IL-2, TNFα, and IFN-γ." (PMID 36614197, 2023).
tumor (continued). "Innate immune cells, such as M1 macrophages, tumor associated granulocytes, and classical monocytes, are known to exert anti-tumor effects with increased proinflammatory cytokines, including IL-1β, IL-6, and TNF-α, and reactive oxygen species." (PMID 38125025, 2023). "In addition, a correlation between TNF-α overexpression and an increased risk of tumor development in vivo has been observed." (PMID 37047539, 2023). "In HL, cytokines such as IL-21, TNF, and IL-1 may be implicated in the inflammatory responses of the tumor microenvironment." (PMID 37958472, 2023). "Excessive UVB irradiation of skin cells produces a large amount of intracellular reactive oxygen species (ROS) that predisposes to an inflammatory cascade of skin photoaging, such as tumor necrosis factor-α (TNF-α)-induced inflammatory pathways through activation of nuclear factor-κB (NF-κB)." (PMID 37686273, 2023). "Currently, there is evidence that inflammatory cytokines and chemokines such as TNFα, IL-1β, and IL-6 may be produced by tumor cells and/or tumor-associated leukocytes and platelets and may directly contribute to malignant progression." (PMID 38137888, 2023). "This may be due to in malnourished patients with cancer tumor cell-mediated cytokines such as IL-1, Il-6, and (TNF-α) cause hemolysis, lowering Hgb levels." (PMID 36869395, 2023). "Our previous study found that irradiation of NSCLC cell lines A549 and H1299 can cause overexpression of TGFβ and TNFα, resulting in HIF1α activation and cause genomic instability of BMSCs and may promote tumor progression." (PMID 36865554, 2023). "Similarly, another study recruiting HCC patients with early or intermediate disease (Barcelona Clinic Liver Cancer-0-B (BCLC-0-B)) also showed that a higher TNF-α expression in tumor tissue was associated with a better postoperative survival." (PMID 37958479, 2023). "The TNF-related lncRNA signature was tightly associated with the regulation of tumor immune therapy and could serve as an independent prognostic biomarker in GBM." (PMID 37153654, 2023). "Interestingly, elevated serum IL6 and TNF levels were found associated with tumor recurrence in NSCLC patients." (PMID 37085672, 2023). "Treatment with anti-CLDN18.2-anti-CD28 also produced more interferon-γ (IFN-γ) and tumour necrosis factor-α (TNF-α) in splenocytes and reduced the levels of immunosuppressive cells, including tumour-associated macrophages and myeloid-derived suppressor cells, in tumour tissues." (PMID 36969060, 2023). "Hypoxia can trigger the expression of genes like TNF-α, IL-18, and H1F-1 in TAMs, which may cause inflammation, angiogenesis, and tumor growth." (PMID 38033495, 2023). "Therefore, more studies evaluating the role and utility of circulating, hepatic, and tumor TNF-α specifically in patients with NAFLD-associated HCC are warranted in the near future." (PMID 37958479, 2023). "By analyzing tumor immune-related cytokines, they suggested that the combination of IFN and TNF-α cytokines may be the mediators of cell death in JMJD6-deficient tumor cells." (PMID 35359945, 2022). "They include a lack of antigenic mutations, disruption of the antigen-processing machinery, loss of major histocompatibility complex (MHC) expression, and defects in interferon-γ (IFN-γ)- or tumor necrosis factor (TNF)-mediated signaling pathway that acts to increase tumor immune susceptibility." (PMID 35094065, 2022). "The “seed and soil” theory postulates that tumor cells produce several tumor-associated factors, including interleukins (IL-1β, IL-6, IL-8, IL-11, IL-17), macrophage inflammatory protein 1α, TNFα, parathyroid hormone-releasing protein (PTHrP), and prostaglandin E (PGE2)." (PMID 36294305, 2022). "In the inflammatory loop of T2DM homoeopathy, two factors, TNF-α and IL-1β, also occupy an important position, among which TNF-α tumor necrosis factor, which functions to cause tumor chemise necrosis and tumor cell death, has a wide range of biological activity." (PMID 35979044, 2022).
tumor (continued). "In addition to its direct toxic effect on tumor cells, the antitumor activity of TNF-α has also been associated with indirect effects of damage to the micro- and macro-vasculature in tumor and stimulation of immune responses." (PMID 36324671, 2022). "A more detailed enrichment indeed shows an increase in TNF-alpha associated signaling which might indicate an increase in tumor-associated immune modulation." (PMID 35600369, 2022). "Tumor-induced inflammation has been found to contribute to muscle depletion and dysregulation of skeletal muscle physiology with pro-inflammatory cytokines such as interleukins and TNF-α, as causative mediators." (PMID 35296013, 2022). "Biologically, TNF comprise a family of cytokines that can damage tumor cells and cause necrosis." (PMID 35509624, 2022). "In addition, NK cell mediated secretion of IFN-γ and TNF-α as well as their percentages were found to be impaired in association with tumor-associated monocytes/macrophages." (PMID 35203349, 2022). "TNFα can also be directly secreted by tumor-associated macrophages and Th17 cells." (PMID 35056404, 2022). "NKp46 has been associated with good prognosis in human NSCLC (owing to the formation or maintenance of tertiary lymphoid structures (TLS), release of IL-22, TNF-α, IL-8, and IL-2 and recognition of lung tumour cells and tumour-associated fibroblasts via the NKp44 receptor." (PMID 35406451, 2022). "Additional molecular biomarkers identified throughout the inflammatory microenvironment of VS that may contribute toward tumor-induced hearing loss include tumor necrosis factor alpha (TNFα), IL-6, CXCR4, and nuclear factor kappa-B (NFκB) activation." (PMID 35372070, 2022). "In addition, ANXA2P2 had significant association with common tumor-related regulatory genes such as TNF-α signaling via NF-κB, TGF-β signaling, DNA repair, hypoxia, autophagy, pyroptosis, and ferroptosis." (PMID 35211410, 2022). "Due to the initial observations that TNF could cause tumor necrosis TNF therapy was tested in clinical trials of cancer." (PMID 35432372, 2022). "In mechanism, obese adipose tissue is regarded as chronically inflammation tissues, through expressing inflammatory cytokines such as IL-1beta, IL-6, IL-10, and TNF-alpha, cancer-associated obese adipocyte recruits macrophages, neutrophils and other immune cells into tumour microenvironment." (PMID 35296087, 2022). "During the process of tumor cell death, inflammation could be induced and related inflammatory cytokines such as TNF-α, IL-1β, and IL-6 further cause immune cell infiltration, which further results in the elimination of dead cells." (PMID 35402247, 2022). "Moreover, a link between high levels of TNF-α and an increased risk of tumor formation and development has been described in vivo." (PMID 36077992, 2022). "The results suggested that inflammation-associated biological processes including interleukin-8 production and response to TNF were markedly enriched in the high-risk group, thus further confirming the close relationship between inflammatory responses and tumor progression." (PMID 35647198, 2022). "In addition, the TNF signaling pathway that causes apoptosis in tumor cells, is an exogenous pathway triggered by the cell surface death receptor tumor necrosis factor receptor family." (PMID 36550159, 2022). "CHMP4C and TNF, as high-risk genes for tumor promotion, positively correlate with promoting tumor progression immune-related cells such as activated mast cells and resting dendritic cells, and negatively correlate with protective immune-related cells such as naïve B cells and CD8+ T cells." (PMID 35574296, 2022). "Importantly, in vivo, the hypersecretion of TNF by NKG7 deficient CD8+ T cells compensates for reduced perforin-mediated control of MC38-OVA tumors through enhanced TNF-mediated tumor cell death." (PMID 35874669, 2022).
tumor (continued). "Of note, prolonged systemic anti-TNF therapy is associated with an increased risk of reactivation of chronic infections such as Mycobacterium tuberculosis and increased risk of neoplasia." (PMID 35408882, 2022). "An increase in the level of TNF-α, on the one hand, accompanies the induction of apoptosis; on the other hand, it stimulates neoangiogenesis and causes an increase in the death of lymphocytes infiltrating the tumor." (PMID 36286034, 2022). "This raises concerns as to whether high plasma levels of TNF–α are associated with neoplasia or inflammatory response towards malignancy." (PMID 35886021, 2022). "However, as a result of inefficient cytotoxic activity, NKG7 deficient T cells form a prolonged immune synapse with tumor cells, resulting in increased secretion of inflammatory cytokines, including tumor necrosis factor alpha (TNF)." (PMID 35874669, 2022). "In addition, after combined treatment with γ-radiation, the tumor size inhibition was enhanced by re-enforcing the elevated levels of TNF-α, VEGF-A, serum MMP-2 and MMP-9, and CAT in liver caused by BV or MEL alone." (PMID 36238572, 2022). "They, in turn, begin secreting their own inflammatory cytokines such as IL-6 and tumor necrosis factor (TNF), producing caustic reactive oxygen species (ROSs) that seep into the tumor and induce apoptosis, and intensifying their phagocytic engulfment of diseased or damaged cells." (PMID 36123677, 2022). "Initially, exogenous TNF-α was observed to cause hemorrhagic necrosis of tumors and promote tumor vascular destruction, so it was considered one of the anti-cancer cytokines that could inhibit tumor progression." (PMID 35965509, 2022). "Interestingly, while both methods implicated IL1β+ macrophages as the drivers of anti-tumor TNF+ mast cell behavior, the full suite of their top results offered little overlap." (PMID 35572582, 2022). "To corroborate our in vitro characterisation studies in preclinical disease models, we constructed transmorphic particles bearing a transgene encoding TNFα, a known anti‐tumour cytokine, for the treatment of NOD/SCID immunodeficient mice bearing subcutaneous GBM001 tumours." (PMID 35758207, 2022). "In addition, TNF-α can also increase the malignancy and adhesion of tumor cells to vascular endothelial or lymphatic endothelium, and tumor cells through lymphatic or blood-transfer risk." (PMID 36226059, 2022). "In the intestinal tract, tumor-associated bone marrow cells secrete IL-23, which affects the polarization of Th17 cells, followed by the production of IL-17A, IL-21, TNF-α, and IL-6, which induce a tumor-promoting inflammatory response and promote CC development." (PMID 36147322, 2022). "Toxicity associated with systemic TNF administration or release beyond the tumor milieu remains a problem which could be addressed if specific and directed release to cancer cells could be attained." (PMID 35574362, 2022). "Tumor-associated macrophages facilitate the PD-L1 expression in GC via IL-6 and TNF-α signals." (PMID 35719369, 2022). "The association of M1-like macrophages with tumor metastasis may be partly due to the effects of inflammatory cytokines, such as IL-1β, TNF-α, and IL-6, which directly or indirectly contribute to vasoproliferation." (PMID 35844605, 2022). "These signals promote the activation of dendritic cells (DCs) and, as a result, the release of pro-inflammatory cytokines such as IL-1β, IL-6, IL-12, and TNFα, and facilitate the engulfing of dying cancer cells following tumour-associated antigen (TAA) presentation to the T cells." (PMID 36140243, 2022). "Evidence has been provided that the CCL2-CCR2 axis can be stimulated by tumor necrosis factor alpha (TNF-α) from tumors cells in the tumor development to further recruit tumor-associated macrophages(TAMs) who helps cancer cells escape from immune system, and finally prompt the development of tumor." (PMID 36685497, 2022).
tumor (continued). "Similarly, the mechanism of anticancer potential is plausibly mediated through upregulation of STAT1 gene (tumor suppressor), and downregulation of IL-6, TNF-α, and CD40 (tumor causing genes) besides other intricate mechanisms." (PMID 36612248, 2022). "Thus, elevated serum IL6 and TNFα levels were found associated with tumor recurrence in NSCLC patients." (PMID 35688943, 2022). "At least, in theory, that might mean that the tumor vessels are susceptible to anti-TNF-α treatments, so the biologic therapies have an antineoplastic effect." (PMID 35563587, 2022). "Mesenchymal transition from another subtype is associated with highly elevated levels of tumor-associated macrophages (TAMs) and tumor-infiltrating T cells; the upregulation of the NF-κB pathway via increased TNF-α (tumor necrosis factor-α) signaling in the TME; and deactivation of NF1." (PMID 35690784, 2022). "First, coculture with tumor cells inhibited the expression of M1-related genes encoding IL-6, TNF-α, and IL-1β and increased the expression of M2-related genes encoding CD163, Arg1, IL-10, TGF-β, and VEGFA, as well as expression of TNF-α and CD163 at protein level." (PMID 34093857, 2021). "However, our results suggest ex vivo neutralization of TNF-α alone is sufficient to abrogate the anti-tumor effect of PD-1 deficient ILC2s." (PMID 34531874, 2021). "Similarly, weekly intraperitoneal injections of anti-TNF monoclonal antibodies starting at the end of the first DSS treatment were associated with a reduced tumor number and size in C57BL/6 mice." (PMID 33917839, 2021). "The cytokines IFN-γ, TNF-α, granzyme B and the membrane protein CD107a are phenotypic markers whose combinatorial expression by lymphocytes is associated with cytotoxic function in multiple contexts, including clinically effective anti-tumor responses." (PMID 34584159, 2021). "Elevated NF-κB activity was associated with tumor resistance to anticancer therapy, as well as to TNF-α-induced apoptosis, which might help these cells evade immune surveillance." (PMID 33924755, 2021). "Thus, promoter methylation in tumours can result in silencing of critical tumour suppressor genes, and this has been demonstrated with methylation of both DNA and histones in the promotor region of the gene encoding cytokine TNF-α in melanoma cell lines." (PMID 34822659, 2021). "Additionally, TNFα-MT is related to high immunogenicity (tumor mutational burden, neoantigen load, and DNA damage response signaling mutations) and enrichment of infiltrating immune cells." (PMID 34603277, 2021). "Six decades later the group of Dr. Lloyd Old identifies an LPS-induced protein with profound hemorrhagic necrotic activity against tumors (mainly mediated by apoptosis in tumor-associated vasculature), as the active principle of Coley’s toxins and named it Tumor Necrosis Factor (TNF)." (PMID 35264975, 2021). "We hypothesized that the mobilization of Th1 cells and the upregulation of TNF-α in the inflammatory tumour microenvironment could be the cause of this up regulation." (PMID 34345201, 2021). "Furthermore, FATS deficiency increased IFN-γ and TNF levels in B16 tumor-infiltrating CD4+ T cells, suggesting enhanced Th1 responses." (PMID 34262035, 2021). "In previous studies, we have shown that low doses of NGR-TNF, a peptide-TNF fusion protein that targets the tumor vasculature, are sufficient to cause the disassembly VE-cadherin dependent-adherence junctions and gap formation in the tumor endothelium, thereby increasing vascular permeability." (PMID 33952242, 2021).